TMEM97 (transmembrane protein 97)
Diseases named in the same sentence as TMEM97 in open-access papers (continued):
Sharing a sentence is not in itself a finding about the gene and the disease.
pancreatic cancer (15 papers, 2007 to 2024). "Our next generation sequencing (NGS) transcriptomic data showed that the σ-2 receptor mRNA TMEM97 was expressed in both primary pancreatic cancer cell culture, at significantly higher values compared to the normal human pancreatic ductal epithelial HPDE cells." (PMID 35268783, 2022). "The data suggest that TMEM97 expression is differentially regulated by TGF-β expression in different pancreatic cancer cell lines." (PMID 32668577, 2020). "TMEM97 was transiently downregulated by TGF-β in two pancreatic cancer cell lines Colo-357 and Panc-1." (PMID 32668577, 2020). "TMEM97 is strongly expressed in the pancreas and other gastrointestinal tissues and is downregulated in pancreatic cancer." (PMID 18070364, 2007). "Furthermore, the expression levels of both TMEM97 protein and mRNA were lower in tumor tissues compared to adjacent normal tissues in pancreatic cancer and kidney cancer." (PMID 37404478, 2023). "The effects of TGF-β on TMEM97 mRNA expression were examined in pancreatic cancer cell lines." (PMID 32668577, 2020). "Knowing that tubular complexes are considered as potential pre-neoplastic lesions, The observed reduction of TMEM97 expression in pancreatic cancer suggests that this gene might act as a tumor suppressor in this disease." (PMID 30574087, 2018). "Here, we investigate the contributions of TMEM97 and TSPO to S2R activity in MCF7 breast adenocarcinoma and MIA PaCa-2 (MP) pancreatic carcinoma cells." (PMID 37047353, 2023). "In contrast, TMEM97 expression was not affected by TGF-β in five other pancreatic cancer cell lines." (PMID 32668577, 2020). "50% of pancreatic cancer biopsies displayed a lower TMEM97 mRNA expression compared to normal pancreatic tissue, 20% displayed no change and 30% presented higher TMEM97 mRNA levels." (PMID 30574087, 2018).
glioma (8 papers, 2016 to 2024). A benign or malignant brain and spinal cord tumor that arises from glial cells (astrocytes, oligodendrocytes, ependymal cells). "Increased expression of TMEM97 has also been associated with the inferior survival of glioma patients." (PMID 38167429, 2024). "The sigma-2 receptor (TMEM97) is highly expressed in human glioma tissues and its expression level is associated with the malignancy of glioblastoma." (PMID 31109310, 2019). "TMEM97 expression is substantially increased in glioma tissues compared to non-tumoral brain tissues, and its expression is increased with higher glioma grades." (PMID 38167429, 2024). "In these studies, TMEM97 knockdown in commonly used glioma (U373, U87) and gastric cancer (AGS, BGC-823) cell lines resulted in decreased cell proliferation, migration, and invasion in in vitro assays." (PMID 31695608, 2019). "In contrast, TMEM97 contributes to xenografted tumor growth using glioma and gastric cancer cell line models." (PMID 31695608, 2019). "Remarkably, increased TMEM97 expression correlated with shorter survival in glioma, ovarian, non-small cell lung, and colorectal cancer patients." (PMID 29599847, 2018). "TMEM97 is found deregulated in several types of cancer but this protein has been particularly involved in the tumor growth of two cancers: glioma and gastric cancer." (PMID 30574087, 2018). "Genes, such as IFIT2, CCR10, and TMEM97, are important for the invasion of various cancer cells, such as oral cancer, melanoma, and glioma, but these genes may be responsible for the invasion of BRCA cells." (PMID 31311202, 2019). "The suppression of TMEM97 could inhibit the proliferation, migration, and invasion of U87 and U373 human glioma cell lines." (PMID 31109310, 2019). "The knockdown of the TMEM97 gene expression by specific siRNA could inhibit cell growth, migration, and invasion of glioma cell lines U87 and U373." (PMID 31109310, 2019). "TMEM97 was recently identified as the sigma-2 receptor and is expressed by human glioma cell lines." (PMID 31109310, 2019). "Indeed, the silencing of TMEM97 expression in glioma U373 and U87 cells inhibited cell proliferation and cell cycle progression associated with a decrease in cyclin B1, E, CDK2 and CDK4 expression, but also in cell invasiveness." (PMID 30574087, 2018). "Interestingly, in glioma cells, TMEM97 depletion inhibited cancer cell growth and metastasis formation, in parallel with deregulation of EMT-related genes." (PMID 29599847, 2018). "Although no information is available for the role of NOL4 in cancer, TMEM97 has been shown to be upregulated in several malignancies, including glioma as well as colorectal and ovarian cancers." (PMID 29599847, 2018).
ovarian carcinoma (8 papers, 2007 to 2025). A malignant neoplasm originating from the surface ovarian epithelium. "To test for somatic mutations in the TMEM97 gene, which is located on chromosome band 17q11.2, we sequenced all of the coding nucleotides (528 base pairs), that are distributed to three exons, in 39 ovarian cancer samples." (PMID 18070364, 2007). "TMEM97 mRNA and/or proteins was significantly increased in breast, colon, gastric, esophageal, lung, ovarian cancer and prostate cancer, but decreased in meningiomas, pancreatic and renal cancer." (PMID 32668577, 2020). "In this context, upregulation of TMEM97 in OSE cells by progesterone was proposed to protect against the development of ovarian cancer." (PMID 31695608, 2019). "The coding nucleotides of TMEM97 in 39 ovarian cancer samples were sequenced." (PMID 32668577, 2020). "Nevertheless, TMEM97 is reported to be upregulated in cancer cell lines and tumors including esophageal, gastric, colorectal, breast, ovarian surface epithelium (suggesting a role in ovarian cancer), oral squamous, and non-small cell lung cancer (NSCLC)." (PMID 31695608, 2019). "This suggests a mechanism to explain a decade of data demonstrating that σ2R/TMEM97 correlates with worse outcomes in a variety of solid tumors, including gastric, non–small cell lung, squamous cell lung, and ovarian cancers." (PMID 39804138, 2025). "No coding sequence variations were found, suggesting that the TMEM97 coding sequence is not responsible for ovarian cancer development." (PMID 32668577, 2020). "Expression of Sigma2/TMEM97, along with several cholesterol biosynthesis genes, was reported to be induced by progesterone in ovarian surface epithelial (OSE) cells, the cell type from which ovarian cancer often derives." (PMID 31695608, 2019).
depression (7 papers, 2017 to 2025). "In addition, loss of σ2R/TMEM97 reduced long-term neuropathic-pain-induced depression-like phenotype in female mice at 10 weeks after nerve injury." (PMID 41008535, 2025). "Global knockout of σ2R/TMEM97 shows less anxiety-like and depression-like behaviors in some conditions, such as light/dark preference and tail suspension tests, but not in others, including open field, elevated plus maze, and forced swim tests at baseline." (PMID 41008535, 2025). "We next performed spared nerve injury in WT and Tmem97 KO mice to assess the role of Tmem97 in neuropathic pain-induced anxiety and depression." (PMID 38866499, 2024). "When we evaluated the full affective phenotype or “emotionality,” we found that Tmem97 disruption decreased anxiety-like and depression-like behavior." (PMID 38866499, 2024). "σ2R/TMEM97 is shown to be associated with several neurological disorders, including anxiety, depression, and addiction." (PMID 36456686, 2022). "Pharmacological agents developed to target the sigma-2 receptor/TMEM97 (s2R/TMEM97) have demonstrated promising effects in alleviating anxiety, depression, and pain individually." (PMID 38866499, 2024).
retinal degeneration (7 papers, 2017 to 2025). Degeneration of the retina. "While an involvement of TMEM97 in RPE physiology and associated retinal degeneration has been implicated in our and others’ reports, the molecular/cellular function of TMEM97 remains poorly understood." (PMID 39995975, 2025). "In an oxidant-induced retinal degeneration model, we observed that photoreceptor loss was exacerbated in Tmem97−/− mice compared to Tmem97+/+ mice." (PMID 36553653, 2022). "This study illustrated that EC, which may become a promising therapeutic strategy for AMD, prevented NaIO3-induced retinal degeneration, and this improvement may be associated with the mitochondrial quality control and the TMEM97/PGRMC1/Aβ signaling pathway." (PMID 35833100, 2022). "In our previous study using the NaIO3-induced RPE damage model, we observed exacerbated retinal degeneration in Tmem97−/− mice compared to Tmem97+/+ controls." (PMID 39995975, 2025). "Our previous study showed that TMEM97/S2R ablation exacerbated retinal degeneration in sodium iodate-treated mice." (PMID 36553653, 2022). "A previous study presented that in a mouse model of oxidative retinal degeneration, TMEM97 knockout exacerbated oxidative stress response, thereby aggravating oxidative retinal degeneration." (PMID 35979045, 2022). "In addition, with limited knowledge available on the role of TMEM97 in retinal degeneration, caution should be taken in future pharmacological interventions targeting TMEM97." (PMID 39995975, 2025). "Thus, to validate our findings in vivo and establish their relevance in broader pathophysiological contexts, further studies are required, preferably incorporating conditional TMEM97 KO, additional retinal degeneration models, and patient-derived samples." (PMID 39995975, 2025). "For instance, while TMEM97 deficiency exacerbated photoreceptor loss in an oxidant-induced RPE-damage model, other studies suggested that pharmacological inhibition of TMEM97/S2R could be beneficial in different retinal degeneration models." (PMID 39995975, 2025). "Thus, whether TMEM97-associated pEMT promotes or mitigates RPE damage and retinal degeneration remains to be delineated." (PMID 39995975, 2025). "Studies, including ours, indicated that TMEM97 is involved in RPE cell stress responses and retinal degeneration." (PMID 39995975, 2025). "σ2R/TMEM97 knockout decreased retinal IL1β and CCL2 expression and alleviated inflammation in a NaIO3-induced retinal degeneration model." (PMID 41008535, 2025). "We re-expressed TMEM97 locally in the RPE of Tmem97−/− mice and observed an amelioration of retinal degeneration." (PMID 39995975, 2025). "Further investigation into the TMEM97—| CTNND2 → ADAM10 pathway may lead to precise and actionable therapeutic strategies to treat retinal degeneration." (PMID 39995975, 2025). "We demonstrated that TMEM97 and PRGMC1 may be involved in the pathological mechanism of retinal degeneration via Aβ accumulation." (PMID 35833100, 2022).
breast tumor (6 papers, 2003 to 2023). "The observations suggest that the TMEM97/sigma 2 receptor is a novel regulator of ERα activities in breast tumor cell growth." (PMID 38067394, 2023). "To determine whether TMEM97 is required for breast tumor growth, we performed shRNA-mediated TMEM97 knockdown experiments on the MCF7 cells." (PMID 38067394, 2023). "High expression of TMEM97 is found in breast tumor tissues with estrogen receptor positivity." (PMID 38067394, 2023). "Next, we determined whether TMEM97 promotes the colony formation of breast tumor cells." (PMID 38067394, 2023).
colorectal cancer (6 papers, 2010 to 2025). A primary or metastatic malignant neoplasm that affects the colon or rectum. "Of note, several reports suggest overexpression of TMEM97, otherwise known as MAC30, and a correlation with poor outcome in lung and colorectal cancer." (PMID 33466391, 2021). "For example, TMEM97 silencing with siRNA increased E-cadherin but decreased N-cadherin and vimentin in HCT116/R and SW480/R colorectal cancer cell lines." (PMID 39995975, 2025). "In colorectal cancer, YY1 was shown to transcriptionally regulate transmembrane protein 97 (TMEM97), leading to downstream modification of GSK3β via phosphorylation." (PMID 38539569, 2024). "TMEM97 cytoplasmic expression was shown to be positively correlated to expression of PCNA; this gene is considered a prognostic factor in the metastasis of colorectal cancer." (PMID 20158880, 2010). "However, we should emphasize that both σ1 and σ2/TMEM97 showed the highest expression levels in NCI-H460 (non-small cell lung cancer) and HCT-15 (colorectal cancer) cell lines." (PMID 33466391, 2021).
melanoma (6 papers, 2007 to 2023). A malignant, usually aggressive tumor composed of atypical, neoplastic melanocytes. "Hence, we analyzed RNAseq data from the TCGA (The Cancer Genome Atlas) and GTEx projects to determine the transcript levels of TMEM97 in patients with melanoma compared to those in healthy patients." (PMID 37298633, 2023). "Our findings would suggest the opposite for TMEM116 in melanoma, and as such it may be like TMEM97, which reportedly has decreased expression in some tumor types and increased expression in others (thus showing both tumor suppressive and oncogenic behaviors in a tissue-dependent context)." (PMID 33963380, 2021). "Through siRNA-mediated knockdown of TMEM97, coding for S2R, we validated the BS148 target in melanoma cells." (PMID 37298633, 2023).
Niemann-Pick disease, type C1 (6 papers, 2019 to 2025). Type C Niemann-Pick disease associated with a mutation in the gene NPC1, encoding Niemann-Pick C1 protein. "The last hypothesis about σ2 receptors identity has been proposed by Alon and colleagues in 2017, when the σ2 receptor was identified as the TMEM97 (also known as MAC-30), an ER resident protein involved in cholesterol homeostasis and in the Niemann–Pick type C disease as NPC1-interacting protein." (PMID 34205334, 2021). "Knockdown of σ2R/TMEM97 upregulates NPC1 expression, reduces cholesterol accumulation, and improves cholesterol trafficking in a cell model of Niemann–Pick type C1 disease." (PMID 41008535, 2025). "TMEM97 is the recently identified σ2 receptor that binds to the intracellular cholesterol trafficking protein NPC1 (Niemann-Pick disease, type C1), reducing its abundance and in turn cholesterol transfer to the ER." (PMID 30578317, 2019).
gastric cancer (5 papers, 2018 to 2025). A primary or metastatic malignant neoplasm involving the stomach. "The downregulation of TMEM97 in gastric cancer BGC-823 and AGS cell lines inhibited the cell proliferation and mobility with a decrease in Akt phosphorylation, hence suggesting that Akt may mediate the TMEM97-induced inhibition of proliferation." (PMID 30574087, 2018). "Additionally, silencing σ2R/TMEM97 in human gastric cancer cells inhibits cancer cell growth, suggesting that σ2R/TMEM97 may be a potential therapeutic target in these types of cancers." (PMID 41008535, 2025).
lung carcinoma (5 papers, 2017 to 2023). "The expression of TMEM48 and TMEM97 are potential prognostic biomarkers for lung cancer, while TMEM45A and TMEM205 are implicated in tumor growth and invasion." (PMID 38248651, 2023). "Indeed, some TMEMs such as TMEM48 or TMEM97 are defined as potential prognostic biomarkers for lung cancer." (PMID 30574087, 2018).
pancreatic adenocarcinoma (5 papers, 2007 to 2023). "We explored the expression of S1R and TMEM97/S2R genes in a panel of cell lines representative of pancreatic adenocarcinoma." (PMID 31156430, 2019). "In agreement with previous data reporting higher density of S2R in several lines of breast and pancreatic cancer cells than in the normal (immortalized) cells, pancreatic adenocarcinoma MP and breast adenocarcinoma MCF7 cells were selected because of the density of the TMEM97 and TSPO proteins." (PMID 37047353, 2023).
prostate carcinoma (5 papers, 2018 to 2025). A carcinoma that arises from epithelial cells of the prostate gland. "Overexpression of miR-152-3p suppressed cell viability and invasion potential and downregulated TMEM97 mRNA expression in prostate cancer LNCaP cells." (PMID 32668577, 2020). "According to previous reports, miR-152-3p targets ADAM17 and TMEM97 in non-small cell lung cancer and prostate cancer, inhibiting the activity of tumor cells 30,31." (PMID 32913475, 2020). "It is reported that stable knockout of TMEM97 by CRISPR/Cas9 gene editing decreased cell proliferation in prostate cancer LNCaP cells." (PMID 32668577, 2020). "The data indicate that TMEM97 is a target gene of miR-152-3p and may be related to prostate cancer development and proliferation." (PMID 32668577, 2020).